SNAP23 (synaptosome associated protein 23)
Diseases named in the same sentence as SNAP23 in open-access papers (continued):
Sharing a sentence is not in itself a finding about the gene and the disease.
cancer (18 papers, 2016 to 2025). A tumor composed of atypical neoplastic, often pleomorphic cells that invade other tissues. "Further analysis of TCGA pan-cancer data revealed that both SNAP23 and STXBP2 overexpression were associated with a better prognosis of SKCM." (PMID 36119081, 2022). "Other regulators involved in cancer exosome secretion include neutral sphyngomyelinase 2 (nSMase2), phosphorylated synaptosome-associated protein 23 (SNAP23) and Rab27A/Rab27B." (PMID 33946403, 2021). "In another study on UM proteins secreted from cancer cells, it was demonstrated that exosomal proteins (such as Synaptosomal-associated protein 23(SNAP23), Complement C1s subcomponent GN = C1S) that could involve in ECM remodeling, cancer cell migration, and invasion and metastasis." (PMID 36969177, 2023). "As a potential regulator of cancer cell metabolism, SNAP23 modulates the levels of oxidative phosphorylation (OXPHOS) within mitochondria, thereby influencing the advancement of CRC." (PMID 41274938, 2025). "SNAP23 exhibits high expression across various cell types and plays a pivotal role in the pathogenesis of multiple cancer forms." (PMID 41274938, 2025). "Given that SNAP23 is widely expressed in cell types and plays a big role in various kinds of carcinomas, we choose SNAP23 to further investigation." (PMID 33446221, 2021). "Trans-well and Matrigel assays further revealed that silencing SNAP23 undermines cancer cell migration and invasion capacities." (PMID 27855700, 2016). "To elucidate the mechanisms by which ROS-mediated damage to cancer cells is influenced by SNAP23 regulation of OXPHOS in response to OXA, we focused on mitochondrial function in the context of drug resistance, given that mitochondria are the primary source of ROS in cells." (PMID 41274938, 2025). "In addition to phosphorylation of Syntenin, SNAP23 and Ago2, which control exosome biogenesis in cancers other PTMs regulate the quantity and composition of exosomes by modulating elements of the machinery of exosome biogenesis." (PMID 36320056, 2022). "Thus, by regulating exosome biogenesis, the activation of STAT3/PKM2/SNAP23 pathway contributes to cancer cachexia development." (PMID 36320056, 2022). "Given our findings that SNAP23 knockdown decreased cancer cell proliferation, migration, and invasion and inhibited apoptosis, we sought to hypothesize that SNAP23 might influence cancer progression via inhibiting apoptosis and promoting metabolic process." (PMID 27855700, 2016). "Generally speaking, SNAP23 might influence cancer process via promoting metabolic and inhibiting apoptosis." (PMID 27855700, 2016). "The GO analysis showed that SNAP23 was closely related with metabolic process, which may be a reason for cancer progression." (PMID 27855700, 2016). "Hence, we hypothesize that ROS-mediated damage to cancer cells is subject to the regulatory influence of SNAP23 on OXPHOS." (PMID 41274938, 2025). "In the SNAP23-related gene analysis, the top 45 of 100 highest-ranking genes were closely related to metabolic processes, suggesting that SNAP23 as a key lipid metabolism-related genes and may play an important role in cancer cell metabolic process abnormalities." (PMID 27855700, 2016). "Further to investigate the relationship between SNAP23 and STXBP2 and patient survival, we further analyzed the pan-cancer data in TCGA." (PMID 36119081, 2022). "As such this has been shown in some cancers for e.g. ESCRT components, syntenin, heparanase, small GTPases (such as Rab27A and Rab27B), SNARE proteins (such as SNAP23)." (PMID 35898875, 2022). "Expression of SNAP23, Stx4 and other SNARES are often upregulated during the progression of cancers, indicating that LDL-cholesterol supports invasive potential via multiple Stx4/SNAP23-dependent trafficking events that are often de-regulated in cancer metastasis." (PMID 35806209, 2022).
cancer (continued). "SNAP23 was reported to promote MVB fusion with the plasma membrane, resulting in CD63-positive exosome release after its phosphorylation on Ser110; different studies have shown a colocalization of both SNAP23 and LC3 with the exosomal marker CD63 within MVB-like structures in cancer cells." (PMID 35008395, 2022). "Targeting KRAS-interacting SNAREs with a SNAP23-degrading protease thus also impairs tumorigenesis, further indicating that targeting SNARE proteins may represent a alternative therapeutic opportunity in KRAS-driven cancer." (PMID 31712554, 2019). "With this procedure, we recorded about 100 STED platelet images each, for six different proteins (VAMP7, VAMP8, STX11, SNAP23, TSP1, and VEGF) and for five different categories of platelets; incubated with cancer cells (MCF-7, MDA-MD-231, EFO-21), non-cancer cells (MCF-10A), or no cells at all (R)." (PMID 35729633, 2022).
infection (7 papers, 2017 to 2025). The state of being infected such as from the introduction of a foreign agent such as serum, vaccine, antigenic substance or organism. "The dysregulation of LD homeostasis caused by knocking down SNAP-23 and Syntaxin 4 revealed an important pathway during infection as it correlates with a defect in Chlamydia development." (PMID 32025513, 2019). "Instead, the loss of SNAP-23 and Syntaxin 4 results in a significant increase in Chlamydia-induced LDs, demonstrating that these SNAREs play an important role in controlling LD homeostasis during infection, which ultimately impacts Chlamydia development." (PMID 32025513, 2019). "To test the importance of SNAP-23, Syntaxin 3, and Syntaxin 4 during infection, we depleted HeLa cells of either of these SNAREs using the CRISPR/Cas9 system." (PMID 32025513, 2019). "One possibility is that the increase in LD content observed in SNAP-23 and Syntaxin 4 KD cells during infection is due to a decrease in LD consumption by Chlamydia in these cells." (PMID 32025513, 2019). "Compared to the empty vector control cell line, we observed a ~71% and ~49% higher induction of LD content following infection in SNAP-23 and Syntaxin 4 KD cells, respectively." (PMID 32025513, 2019). "Next, we investigated the impact of SNAP-23, Syntaxin 3, and Syntaxin 4 depletion on LD production during infection." (PMID 32025513, 2019). "Since LD homeostasis is dysregulated during infection in SNAP-23 and Syntaxin 4 KD cells, we assessed the impact of increasing host cell FAs on Chlamydia-induced LDs in the SNAP-23 and Syntaxin 4 KD cell lines." (PMID 32025513, 2019). "Collectively, we verified that two membrane trafficking proteins, STX7 and SNAP23, indirectly interact with MAAP2 during both wtAAV2 infection and rAAV2 production." (PMID 39807420, 2025). "However, infection of the MAAP KO mutant virus, AAV2ΔMAAP, in SNAP23-KO cells released only ∼1% virions in the media, and SNAP23 KO resulted in a significant but slight increase (to ∼2%) in virion secretion." (PMID 39807420, 2025). "Consistent with their involvement in typhoid toxin transport, cells lacking SNAP23 or syntaxin 4 showed markedly reduced levels of typhoid toxin in the infection media." (PMID 35579416, 2022). "Interestingly, SNAP-23 is a t-SNARE for VAMP3, and has also been shown to localize within the vAC during infection." (PMID 32910773, 2020). "However, the release of exosomes by gastroendothelial cells was stimulated by infection with the protozoan parasite Cryptosporidium parvum, in a process involving TLR4/IKK2 signalling and a SNAP23-dependent exocytosis." (PMID 32944186, 2020).
neurodegenerative disease (1 paper, 2024). A disorder of the central nervous system characterized by gradual and progressive loss of neural tissue and neurologic function. "The synaptic proteins such as post-synaptic density protein 95 (PSD-95), synaptophysin (SYN), and synaptosomal associated protein 23 (SNAP23) are essential for regulating various neurotransmitters and have been found to be modified in neurodegenerative diseases." (PMID 39355174, 2024).
SNAP23 also shares sentences with these, for which no sentence is quoted: pancreatic cancer (2 papers); Alzheimer disease (1); asthma (1); autism (1); basophilic leukemia (1); brain ischemia (1); Burkitt lymphoma (1); cardiovascular diseases (1); cervical cancer (1); chronic heart failure (1); chronic obstructive pulmonary disease (1); COVID-19 (1); cystitis (1); diabetic cardiomyopathy (1); Hepatic steatosis (1); hydronephrosis (1); myocardial infarction (1); neurological disease (1); neuropathic pain (1); periodontitis (1); preeclampsia (1); Sjögren’s syndrome (1); Thrombus (1); virus infection (1).